TERT (telomerase reverse transcriptase)
Diseases named in the same sentence as TERT in open-access papers (continued):
Sharing a sentence is not in itself a finding about the gene and the disease.
cancer (continued). "Taken together, TERT or telomerase may contribute to multi-cancer hallmarks via its telomere lengthening-dependent and independent functions." (PMID 31285550, 2019). "Collectively, the aberrant TERT expression and TERT-related genomic alterations may serve as prognostic factors in multiple types of cancer, and the further evaluation including large cohorts of patients is required for future clinical application." (PMID 31285550, 2019). "Indeed, Sp1 inhibition significantly attenuated TERT-mediated DNMT3B up-regulation, while its over-expression restored DNMT3B expression in TERT-depleted cancer cells." (PMID 31911897, 2019). "Thus, there is increasing interest in the role of epigenetic and transcriptional regulation of TERT in cancer." (PMID 31757062, 2019). "The telomerase reverse transcriptase (TERT) gene codes for the core catalytic subunit of telomerase, an enzyme which is responsible for elongating the telomeric ends of chromosomes, thereby enabling cancer cells to bypass senescence." (PMID 31391125, 2019). "Indeed, we and Keith’s group first identified the TERT amplification in human cancer almost 20 years ago." (PMID 31285550, 2019). "However, cancer cells are able to produce full length of functional TERT and develop numerous regulatory mechanisms of TERT activation and stabilization." (PMID 31179925, 2019). "As miRNA dysregulation is widespread in cancer and significantly contributes to carcinogenesis, it is interesting to determine whether such TERT effect plays a part in cancer development and progression." (PMID 31284662, 2019). "Furthermore, mounting evidence indicates a role of TERT in supporting metastatic spreading of cancer by the activation of the epithelial to mesenchymal transition (EMT)." (PMID 31200515, 2019). "Thus, when the p21 level is decreased by TERT in cancer cells, the expression level of CCNB1 can be increased because CCNB1 is no longer inhibited by p21." (PMID 31856825, 2019). "Furthermore, Telomerase-based immunotherapy has also been developed and relies on the possibility of using TERT-derived peptides processed and presented on the surface of cancer cells as cancer neo-antigens, stimulating immune-mediated cell-kill." (PMID 31200515, 2019). "We recognize that stratification of patients by cancer stage and TERT promoter mutation has not been conducted." (PMID 31179925, 2019). "Interestingly, TERT promoter methylation is required for cancer cells to activate TERT transcription, while TERT induction in turn promotes the aberrant methylation by upregulating the expression of DNA methyltransferases, which forms a positive feedback loop." (PMID 31285550, 2019). "Many of the pioneering works (from the early 21st century) utilizing human TERT promoter focused on adenovirus-mediated delivery of suicide genes or apoptosis-inducing genes that are capable of directly inducing cancer cell death." (PMID 31035374, 2019). "Recently, ASF1a has been shown to be up-regulated in certain human malignancies and required for the expression of telomerase reverse transcriptase (TERT), a factor essential for the immortal phenotype of cancer cells; however, its role in oncogenesis remains poorly defined." (PMID 30692519, 2019). "In addition, the mTERT promoter-driven oncolytic adenovirus exhibited markedly higher cancer specificity than did the oncolytic adenovirus replicating under the control of the unmodified human TERT promoter." (PMID 31035374, 2019). "It is currently unclear whether or how much this mechanism contributes to cancer-related TERT transcription, and whether it cooperates with other regulatory cascades to activate telomerase." (PMID 31285550, 2019). "Finally, mutations in the TERT promoter and NRAS, PTEN, and PIK3CA genes are occasional molecular drivers of cancer in the pediatric population." (PMID 31456750, 2019). "In addition, CAF-derived HMGB1 promotes TERT expression in cancer cells and induces stem cell properties." (PMID 31905926, 2019).
cancer (continued). "In this study, BRAF V600E, RETPTC1 rearrangement, and TERT promoter mutations were found to be associated with more aggressive cancers when compared to malignancies without one of these mutations." (PMID 31623671, 2019). "In cancers, rate-limiting factor for telomerase activity is TERT expression." (PMID 29614790, 2018). "TERT has been noted to be enzymatically active in different cancers." (PMID 29614790, 2018). "Moreover, in cancer cells exposed to genotoxic stress, a low nuclear but high cytoplasmic/mitochondria content of TERT protein was correlated with lower levels of ROS, DNA damage and apoptosis." (PMID 30472697, 2018). "Telomerase, a ribonucleoprotein complex containing an internal RNA component (TR or TERC) and a catalytic protein (TERT, Telomerase Reverse Transcriptase), enables telomere elongation; it is active in cancer cells and, transiently, in tissue in rapid proliferation." (PMID 30418933, 2018). "However, circumstantial studies have also highlighted miRNA regulation of TERT in different cancers." (PMID 29614790, 2018). "Importantly, GSK3α is now known as a novel CREB-target gene that promotes the viability of cancer cells and NF-κB-dependent gene transcription of TERT, indicating a reciprocal regulation between CREB and GSK3α." (PMID 29434603, 2018). "Although the results of the meta-analysis suggest this if not the cause in the majority of cases, four cancer studies were included that originally reported an association with the TERT allele for short telomeres." (PMID 29536006, 2018). "No publication bias for the association between TERT rs2853669 polymorphism and cancer susceptibility was manifested based on Begg’s funnel plot (PBegg = 0.921, CC versus TT) or Egger’s regression test (PEgger = 0.652, CC versus TT)." (PMID 29534075, 2018). "In this review we have comprehensively summarized miRNA regulation of TERT in different cancers." (PMID 29614790, 2018). "TERT is directly controlled by miR-138 in different cancers." (PMID 29614790, 2018). "Recently, an interaction has been reported that might be crucial for TERT reactivation across different cancer types." (PMID 29458419, 2018). "Reanalyzing these samples and data, taking in account allele-specific methylation, may present novel insight into the relationship between TERT promoter methylation and cancer." (PMID 29439385, 2018). "TERT is an interesting and safe immunologic target as it is overexpressed mainly by cancer cells." (PMID 30537967, 2018). "Integrin β1 (ITGB1) was significantly increased in TERT over-expressing SGC7901 cancer cells." (PMID 29614790, 2018). "Furthermore, recurrent integration events (≥4) were found at known cancer-related genes, including TERT, resulting in overexpression of these genes in tumor versus normal tissue." (PMID 29677098, 2018). "Interestingly, β-catenin has, in turn, been shown to bind to the TERT promoter, suggesting a possible feed-forward loop that supports stemness and proliferation in wnt-dependent cancers." (PMID 29303978, 2018). "TERT is expressed in germ cells as well as in many types of cancers." (PMID 30226466, 2018). "c-Myc over-expression induced an increase in TERT in FOXM1 silenced SMMC-7721 cancer cells." (PMID 29614790, 2018). "Malignant cancer cells, which were replicative immortal, required activation of telomerase and regulation of other growth controlling genes, pathways and molecular by TERT." (PMID 30619082, 2018). "Findings clearly suggested that miR-202 targeted Mxd1 to increase TERT expression in cancer cells." (PMID 29614790, 2018).
cancer (continued). "Specifically, a fundamental question as to how BRAF V600E and mutant TERT, which each apparently represents a different molecular system, are functionally bridged at the molecular level in cooperatively promoting human cancer aggressiveness remains to be answered." (PMID 29422527, 2018). "TERT has also been reported as a cancer driver of various tissues including thyroid and liver." (PMID 29697361, 2018). "Increasing researches have been performed regarding the relationship between TERT rs2736098 and cancer risk, but no consensus has been reached about the relationship." (PMID 29221218, 2017). "Lastly, we present correlation analyses between Myc and TERT in several cancers." (PMID 28184371, 2017). "We suggested that TERT gene may have relationship with cancers and disease by influencing the balancing the telomere length; however, the mechanistic details have not yet been elucidated." (PMID 28978050, 2017). "Notably, two trunk genes (SPEN and ITK), a branch gene (SMARCE1), and several private genes (FAT4, CACNA1D, ATR, RUNX1T1, TERT, and SRGAP3) were defined as cancer-associated genes, according to the cancer gene census." (PMID 28716121, 2017). "These recent findings suggest that the cooperation of native and changed (mutations, SNP) binding sites for multiple transcriptional factors in the TERT promoter could regulate TERT expression and result in cancer-specific effects of SNP." (PMID 29100407, 2017). "TERT splicing dysregulation is present in many cancers and it is thought that human TERT (hTERT) splicing could be manipulated for therapeutic purposes." (PMID 28441946, 2017). "TERT (telomerase reverse transcriptase), the catalytic component of telomerase, is transcriptionally repressed in normal adult somatic cells, which thus do senesce; but is reportedly re-expressed in 85-90% of human cancers, permitting immortality." (PMID 29262649, 2017). "Thus, investigating transcriptional regulation of TERT is important for understanding cancer development." (PMID 28184371, 2017). "Moreover, both sample sets shared four genes in their ‘top 20’ list of ‘Cancer census genes’ most frequently involved in a copy number gain (i.e. TERT, FCGR2B, CD79B and PRKAR1A)." (PMID 29371938, 2017). "Several molecular events can modify TERT expression in cancer cells." (PMID 29100407, 2017). "For cells that do not have a mutation in the TERT promoter in cancer cases or deficiency in the telomerase activity in age-related diseases, more studies should be performed to search for novel regulators and to characterize them." (PMID 28264499, 2017). "However, telomerase activation is evident in ≥85% of cancers, suggesting that upregulation of TERT expression and telomerase activation is a key step in cancer development." (PMID 29134130, 2017). "While stem cells and cancer cells display high telomerase activity, normal somatic cells lack telomerase activity primarily due to transcriptional repression of telomerase reverse transcriptase (TERT), the catalytic component of telomerase." (PMID 28184371, 2017). "The high recurrence, specificity, and gain of function of non-coding promoter TERT mutations support that they are driver rather than passenger events in cancer development." (PMID 29165358, 2017). "This represents another novel aspect of the crosstalk between Myc and TERT in cancers." (PMID 28184371, 2017). "Our study has identified a novel role of TIP60 in regulating the function of Sp1 at the TERT promoter by acetylating Sp1 at K639 and we speculate that this may be a feature common to all virus-induced cancers." (PMID 29045464, 2017).
cancer (continued). "TERT promoter mutations have been detected at a high frequency in many different cancers as melanoma, non-melanoma skin cancers, bladder cancer, and glioma." (PMID 29165358, 2017). "Telomere shortening could be induced in the cancer cells through downregulating the expression level of telomerase activity along with the decrease in TERT and TERC transcripts’ level." (PMID 30460075, 2017). "Moreover, cycoplasmic TERT has been shown to improve mitochondrial function and contribute to higher resistance of cancer cells against DNA damage induced by oxidative stress." (PMID 28460432, 2017). "This suggests that there may be additional, as yet undiscovered mechanisms operating for regulation of TERT expression through Myc- dependent or independent means in these cancer types." (PMID 28184371, 2017). "However, they shared with carcinomas a similar prevalence of copy gains in several genes, including the chromosome 5p genes TERT, SDHA, and RICTOR, but also SRC and MYCL." (PMID 27873319, 2017). "Of interest, the re-activation of telomerase in cancer cells may affect the cancer’s invasiveness and metastasis through the interaction of TERT with the Wnt/β-catenin and the NF-kB signaling pathways." (PMID 27501725, 2016). "In the pan-cancer cohort, comprising 505 tumors the promoter regions with the most significant FM bias comprise a shortlist of interesting candidate drivers, such as those of TERT, SYF2, ARGHEF18, and POLR2D." (PMID 27311963, 2016). "This could mean that the regulation of TERT expression after rapamycin treatment might be different in brain tissue in vivo where we found an increased TERT expression after rapamycin treatment in mice than in cancer cells in vitro." (PMID 27777385, 2016). "Epidemiological studies have identified several genetic polymorphism loci associated with increased cancer risk on chromosome 5p15.33, which contains two key genes, CLPTM1L (cleft lip and palate transmembrane 1-like) and TERT (telomerase reverse transcriptase)." (PMID 27655710, 2016). "Thus, TERT function affects cell survival and stress resistance, with important implications in inflammation and cancer invasiveness." (PMID 27695477, 2016). "The cancer-specific TERT promoter methylation has previously been tested for clinical significance." (PMID 26870890, 2016). "The function of TERT has been studied in the contexts of aging and cancer." (PMID 27300262, 2016). "First, transcription activators lead to up-regulation of TERT expression in cancer cells." (PMID 27367732, 2016). "In addition, TERT was further shown to protect cancer cells from apoptosis stimulated by various insults or stresses." (PMID 27438857, 2016). "This is probably the reason for cancer-specific effects of SNPs on TERT expression." (PMID 26575952, 2016). "TERT promoter mutations are not acquired in proportion to cancer progression; however, are already encoded in the primary tumors." (PMID 27661004, 2016). "The TERT gene, which encodes the catalytic subunit of telomerase, is expressed in most aggressive cancer cells but is silenced in non-immortalized cells." (PMID 27825130, 2016). "Finally, since ETS factors have been shown to regulate TERT (Telomerase Reverse Transcriptase) in cancer, we specifically examined FOXE1-ELK1 co-regulation of this gene promoter." (PMID 27852061, 2016). "The TERT gene is transcriptionally repressed and telomerase is silent in the majority of normal human somatic cells, whereas the TERT induction coupled with telomerase activation is required for malignant transformation and occurs widely in human cancer including UTUCs." (PMID 26934125, 2016).
cancer (continued). "The relative characteristics and prognostic effects of TERT promoter mutation (pTERTm) on carriers and noncarriers with cancer are unclear." (PMID 26799744, 2016). "Previously, we determined the telomerase activity-independent TERT function may contribute to cancer development and aging independently of telomere lengthening." (PMID 27494887, 2016). "In conclusion, mutations in TERT promoter and in CTNNB1 gene represent specific cancer signatures in the pathogenesis of viral related HCC and could be promising early biomarkers as well as targets for tailored therapies." (PMID 27276713, 2016). "Nevertheless, the telomere lengthening-independent functions of TERT may also play important roles in cancer progression, which eventually leads to poor outcomes as seen in MTC and other cancer patients." (PMID 26870890, 2016). "In addition, we observed that TERT promoter mutations in HCC were associated with older patient age, consistent with other studies in HCC and in in several other cancers." (PMID 27056898, 2016). "Although TERT is not frequently mutated in cancer cells, its overexpression promotes cancer formation by impairing telomere-shortening related senescence." (PMID 26938653, 2016). "TERT appears to influence carcinoma/normal mucosa differential expression." (PMID 27627813, 2016). "However, despite scientifically rigorous analyses of WGS data from a range of cancers, non-coding somatic mutations have yet to be identified with such robust links to cancer development as the TERT and TAL1 regulatory examples." (PMID 26356674, 2015). "Meta-analysis of 85 studies of SNV's and cancer types, but not hematological malignancies revealed associations for several TERT SNV's." (PMID 26298771, 2015). "Long-term inhibition of TERT or interference with telomerase recruitment to telomeres lead to cell death in telomerase-positive cancer and stem cells." (PMID 26194807, 2015). "Recently two cancer-related CRM mutations have been discovered, namely: a highly recurrent mutation in the TERT promoter that is found in many cancer types; and a more distally located enhancer mutation upstream of the TAL1 gene in T-cell acute lymphoblastic leukemia (T-ALL)." (PMID 26562774, 2015). "It is noteworthy that there are no reports concerning the correlation between TERT polymorphisms and clinical outcomes of cancer patients receiving platinum-based chemotherapy." (PMID 26020272, 2015). "In this review, we surveyed TERT expression levels across >3,500 human cancers, including ChRCC." (PMID 25859550, 2015). "It is remarkable that TERT promoter mutations are sufficient to up-regulate TERT expression without additional cancer-selected changes in the genome such as increased levels of ETS factors." (PMID 26194807, 2015). "TERT is of great importance in cancer initiation and progression." (PMID 26020272, 2015). "Unexpectedly, some common cancers, like breast and colon carcinoma, do not harbor TERT promoter mutations." (PMID 26194808, 2015). "Studies indicate that the TERT-CLPTM1L region may harbor multiple elements that have the capacity to influence molecular phenotypes in cancer development." (PMID 26372813, 2015). "Recently, it was shown that TERT interact with NFκB and co-activate the expression of several genes, including cytokines, such as IL-6 and TNFα, that are critical for inflammatory reactions and cancer progression." (PMID 26298771, 2015). "The gain of TERT is the most frequent amplification event occurring in early stage cancers." (PMID 26497366, 2015). "High levels of TERT expression and telomerase activation have been reported in many cancer cells." (PMID 26497550, 2015). "In this review, we look more closely at the TERT promoter and TAL1 enhancer alterations and use these examples to ask whether other cis-regulatory mutations may play a role in cancer susceptibility." (PMID 26356674, 2015).